MED20 (mediator complex subunit 20)
Description:
Component of the Mediator complex, a coactivator involved in the regulated transcription of nearly all RNA polymerase II-dependent genes. Mediator functions as a bridge to convey information from gene-specific regulatory proteins to the basal RNA polymerase II transcription machinery. Mediator is recruited to promoters by direct interactions with regulatory proteins and serves as a scaffold for the assembly of a functional preinitiation complex with RNA polymerase II and the general transcription factors.
Synonyms: TRFP; DKFZp586D2223; PRO0213; SRB2
Tractability: Small molecule: a structure with a bound ligand is known. PROTAC: ubiquitination databases record sites on it; its protein half-life has been measured.
Gene: Protein-coding gene on chromosome 6 (41,905,354 to 41,921,139, reverse strand). Ensembl gene ENSG00000124641.
Subcellular location: Nucleus
Pathways (Reactome):
Gene expression (Transcription): Generic Transcription Pathway; MLL4 and MLL3 complexes regulate expression of PPARG target genes in adipogenesis and hepatic steatosis
Developmental Biology: Transcriptional regulation of white adipocyte differentiation
Disease: RSV-host interactions
Metabolism: PPARA activates gene expression
Gene Ontology:
Molecular function: protein binding; DNA-directed RNA polymerase activity; transcription coactivator activity; transcription coregulator activity
Biological process: DNA-templated transcription; positive regulation of transcription elongation by RNA polymerase II; positive regulation of transcription initiation by RNA polymerase II; regulation of transcription by RNA polymerase II; RNA polymerase II preinitiation complex assembly; transcription by RNA polymerase II
Cellular component: core mediator complex; nucleus; mediator complex; nucleoplasm
Genetic constraint (gnomAD): Loss-of-function variants: 19 observed, 20.96 expected, observed/expected ratio (o/e) 0.91, 90% interval 0.63 to 1.33. The upper end of that interval is the gene's LOEUF score, 1.33, which puts it in group 5 of 6, group 1 being the genes least tolerant of losing a copy. Missense variants: 225 observed, 287.27 expected, observed/expected ratio (o/e) 0.78, 90% interval 0.7 to 0.88. Synonymous variants: 105 observed, 111.16 expected, observed/expected ratio (o/e) 0.94, 90% interval 0.81 to 1.11.
Homologues: Orthologues: chimpanzee MED20 (100% identical), dog MED20 (99% identical), rabbit MED20 (99% identical), pig MED20 (99% identical), guinea pig MED20 (98% identical), mouse Med20 (97% identical), rat Med20 (97% identical), tropical clawed frog med20 (75% identical), zebrafish med20 (67% identical), Drosophila melanogaster MED20 (41% identical), Caenorhabditis elegans mdt-20 (31% identical).
Diseases named in the same sentence as MED20 in open-access papers:
MED20 is named in the same sentence as 35 diseases in open-access papers, as found by Europe PMC text mining. Sharing a sentence is not in itself a finding about the gene and the disease. The quoted sentences say what the papers report.
Obesity (3 papers, 2022 to 2023). Accumulation of substantial excess body fat. "Furthermore, knockdown of MED20 in the early stages of adipogenesis inhibits mature adipocyte formation and lipid accumulation in cells, while mice lacking one allele of MED20 in preadipocytes are protected from diet-induced obesity." (PMID 35184223, 2022).
breast carcinoma (2 papers, 2022 to 2023). "MED20 belongs to a family of transcription factors that mediate transcription of different genes, including, importantly, the estrogen receptor gene among other intracellular receptors, which emphasize the role of this family in breast cancer pathogenesis." (PMID 37511575, 2023). "Hence, it could be that MED20 is connected to breast cancer tumorigenesis in relation to the combination of hyperglycemia and hyperinsulinemia, which indeed requires further exploration." (PMID 37511575, 2023). "Despite silico-derived data being obtained from a small number of patients, we were able to identify ALDH1A3, MED20, PABPC4, SLC26A11 and SCP2 as deregulated genes in diabetic breast cancer patients, which coincided with our microarray data." (PMID 37511575, 2023).
Cerebellar atrophy (2 papers, 2019 to 2025). Cerebellar atrophy is defined as a cerebellum with initially normal structures, in a posterior fossa with normal size, which displays enlarged fissures (interfolial spaces) in comparison to the foliae secondary to loss of tissue. "Siblings homozygous for MED20 pathogenic variants were shown to exhibit severe spasticity, dystonia, progressive basal ganglia and cerebellar atrophy, with childhood onset of cataracts." (PMID 40745490, 2025).
Brain atrophy (1 paper, 2025). Partial or complete wasting (loss) of brain tissue that was once present. "Further, MED20 gene mutations are associated with familial infantile basal ganglia degeneration and brain atrophy." (PMID 40724930, 2025).
COVID-19 (1 paper, 2025). A disease caused by infection with severe acute respiratory syndrome coronavirus 2. "Notably, the other SNP, rs1886814, which is only associated with COVID-19 severity, insignificantly reduces FOXP4 expression but has no distinct effect on LINC01276, FOXP4-AS1, or MED20 expression." (PMID 40724930, 2025).
dwarfism (1 paper, 2021). "The mutation in MED17, MED18, or MED20 resulted in dwarfism, delayed flowering, and reduced fertility." (PMID 33868352, 2021).
Fusarium infection (1 paper, 2017). "In support of our results presented here, an accompanying paper describe that both med18 and med20 mutants show a strong level of resistance to Fusarium infection in Arabidopsis." (PMID 28640868, 2017).
generalized lipodystrophy (1 paper, 2024). Almost complete absence of subcutaneous and/or visceral adipose tissue. "Here, we found that Med20-AKO mice progressively developed lipodystrophy, which mimic the features of acquired generalized lipodystrophy and can be rescued by ROS scavenging." (PMID 38168040, 2024).
lipodystrophy (1 paper, 2024). A congenital or acquired disorder characterized by abnormal loss or redistribution of the adipose tissue in the body. "MED20-deficient adipocytes died of increased ROS production, and Med20-AKO mice developed lipodystrophy." (PMID 38168040, 2024). "We showed that knocking out Med20 in adipocytes induced lipodystrophy in mice, which was largely reversed by either scavenging ROS or inhibiting necroptosis." (PMID 38168040, 2024). "Adipocyte-specific male Med20 knockout mice progressively develop lipodystrophy, which is reversed by scavenging ROS." (PMID 38168040, 2024). "To figure out when Med20-AKO mice started to develop lipodystrophy, we examined the mice at different ages." (PMID 38168040, 2024). "Taken together, adipocyte-specific knockout of Med20 induces progressive lipodystrophy in mice." (PMID 38168040, 2024). "We then explored whether we could rescue the lipodystrophy in Med20-AKO mice by inhibiting necroptosis with NEC-1." (PMID 38168040, 2024). "Overall, scavenging ROS largely reverses the lipodystrophy in Med20-AKO mice." (PMID 38168040, 2024). "Interestingly, preventing necroptosis using NEC-1 also improves the lipodystrophy phenotype and comorbidities; however, inhibition of necroptosis will presumably not resolve the cellular ROS stress induced by MED20 deficiency." (PMID 38168040, 2024). "Similar to BHA, NEC-1 treatment significantly improved the metabolic disorders in Med20-AKO mice and largely reversed the lipodystrophy." (PMID 38168040, 2024).
sleep disorder (1 paper, 2025). A change from the patient's baseline sleeping pattern, in the hours slept and/or an alteration/dysfunction in the stages of sleep. "LINC01276 targets the MED20 gene that expresses mostly in brain tissues, associated with sleep disorders and basal ganglia abnormalities similar to some of the symptoms of PCC phenotypes." (PMID 40724930, 2025). "GWAS studies identified that MED20 polymorphisms are associated with adult sleep disorders." (PMID 40724930, 2025). "Several MED20 mutations are identified in basal ganglia syndrome in familial cases, implicating its importance in brain functions and severe sleep disorder in adults, suggesting that abnormalities in MED20 function may lead to PCC brain phenotypes similar to brain disorders." (PMID 40724930, 2025).
tumor (3 papers, 2021 to 2025). "Intriguingly, multiomics analysis revealed MED20 as one of the signatures related to tumor cells." (PMID 37511575, 2023). "Among them, only three genes—MED6, MED14, and MED20—were found to be highly expressed in LUAD and essential for tumor cell growth." (PMID 40302793, 2025).
MED20 also shares sentences with these, for which no sentence is quoted: atherosclerosis (2 papers); cancer (2); colon cancer (2); developmental delay (2); infection (2); microcephaly (2); oral cancer (2); bacterial infection (1); brain disorder (1); cataract (1); Cerebral atrophy (1); cervical cancer (1); diabetic (1); Dystonia (1); Hyperglycemia (1); Hyperinsulinemia (1); Intellectual disability (1); metabolic disorders (1); metabolic syndrome (1); metastatic cancers (1); morbid obesity (1); neurological disorders (1); periodontal disease (1); prostate carcinoma (1).